KRT1 (keratin 1)
Diseases named in the same sentence as KRT1 in open-access papers (continued):
Sharing a sentence is not in itself a finding about the gene and the disease.
laryngeal carcinoma (1 paper, 2025). Carcinoma that arises from the laryngeal epithelium. "This study investigated the association between KRT1 expression and recurrence in advanced laryngeal cancer." (PMID 41002590, 2025). "KRT1 expression in advanced laryngeal cancer specimens was analyzed, and its associations with clinicopathological features and survival outcomes were evaluated." (PMID 41002590, 2025). "This single-center study investigated the association between KRT1 expression and recurrence in advanced laryngeal cancer and then explored its potential as a therapeutic target." (PMID 41002590, 2025). "The effects of KRT1 expression on clinical outcomes were evaluated in patients with laryngeal cancer." (PMID 41002590, 2025). "This study provides compelling evidence that KRT1 plays a key role in laryngeal cancer recurrence and chemoradioresistance." (PMID 41002590, 2025). "Despite this limitation, this study is the first to identify KRT1 as a potential biomarker in advanced laryngeal cancer using strict inclusion criteria." (PMID 41002590, 2025). "A few studies have indicated KRT1 involvement in premalignant and malignant oral lesions, but its role in laryngeal cancer remains unexplored." (PMID 41002590, 2025). "Findings from this study suggest that KRT1 contributes to laryngeal cancer recurrence and resistance to chemoradiotherapy." (PMID 41002590, 2025). "After KRT1 had been identified via RNA sequencing and TCGA dataset analysis, immunohistochemical evaluation was performed on tissue samples from patients diagnosed with advanced laryngeal cancer who underwent definitive CCRT." (PMID 41002590, 2025). "KRT1 may serve as a biomarker for predicting advanced laryngeal cancer recurrence and assist with selecting patients to receive concurrent chemoradiotherapy (CCRT)." (PMID 41002590, 2025). "Although these results are preliminary, we propose that KRT1 may function as an innovative biomarker for predicting prognosis and aid in patient selection for concurrent chemoradiotherapy for laryngeal cancer treatment." (PMID 41002590, 2025). "Thus, KRT1 has potential not only as a therapeutic target but also as a predictive biomarker to guide initial treatment selection between surgery and chemoradiation in patients with advanced laryngeal cancer." (PMID 41002590, 2025). "This study investigates the role of Keratin-1 (KRT1), identified through RNA sequencing as a potential target molecule for laryngeal cancer, in the tumor progression and chemoradioresistance of laryngeal cancer cells." (PMID 41002590, 2025).
leiomyoma (1 paper, 2016). A well-circumscribed benign smooth muscle neoplasm characterized by the presence of spindle cells with cigar-shaped nuclei, interlacing fascicles, and a whorled pattern. "In addition, PTRF co-expresses with KRT1, CCT5 co-expresses with MHI1; GOT1 co-expresses with MHI1; and MHI1 co-expresses with LDHB; indicating not only an interaction between LDHB, GOT1 and MDH1, but also a possible association between them and the leiomyoma." (PMID 27070597, 2016). "KRT1 may regulate the activity of kinase PKC, which is involved in leiomyoma growth control." (PMID 27070597, 2016).
leprosy (1 paper, 2022). Leprosy is a chronic infectious disease affecting primarily the skin and peripheral nervous system. "Furthermore, the BCEs of the host protein Keratin 1 may be useful to predict T1R in leprosy." (PMID 36560940, 2022).
myocardial ischemia (1 paper, 2021). A disorder of cardiac function caused by insufficient blood flow to the muscle tissue of the heart. "Furthermore, it has been reported that inhibition of KRT1 expression can improve myocardial ischemia–reperfusion injury by activating Notch signaling pathway." (PMID 34301176, 2021).
Obesity (1 paper, 2025). Accumulation of substantial excess body fat. "The network of upregulated proteins demonstrated a dense interaction architecture with KRT1 and MYH9 emerging as key hub nodes, suggesting their potential core roles in the functional transformation of VAT in obesity." (PMID 40822952, 2025).
pterygium (1 paper, 2021). A wedge-shaped fibrovascular lesion arising from the bulbar conjunctiva and extending to the cornea. "In our study, we found only minimal changes, with modest upregulation of KRT10 in pterygium and no expression of KRT1 in either pterygium or pinguecula; in addition, FLG2 was modestly upregulated in pinguecula." (PMID 34769520, 2021).
skin squamous cell carcinoma (1 paper, 2020). A carcinoma arising from the squamous cells of the epidermis. "A previous study showed that both EGFR small interfering RNA (siRNA) and EGFR inhibitors increase the expression of several differentiation markers, including keratin 1, keratin 10, and involucrin in primary human keratinocytes, intact epidermis, and skin squamous cell carcinomas." (PMID 33096942, 2020).
staphylococcus aureus infection (1 paper, 2020). An infectious process in which the bacteria Staphylococcus aureus is present. "The expression patterns of proteins involved in the tight junction pathway (related genes: Tuba, PAR6, AMPK, Myosin II, CRB3, JARB, and ZO-3) and Staphylococcus aureus infection pathway (related genes: PLG and KRT1) also show synergistic regulation effects of GA and GKW." (PMID 32765254, 2020).
Stevens-Johnson syndrome (1 paper, 2020). Stevens-Johnson syndrome is a limited form of toxic epidermal necrolysis characterized by destruction and detachment of the skin epithelium and mucous membranes involving less than 10% of the body surface area. "KRT10 expression is associated with ocular surface diseases like Stevens Johnson syndrome and superior limbic keratoconjunctivitis, and KRT1/KRT10 are not expressed in healthy conjunctival tissue." (PMID 32929145, 2020).
thyroid autoimmunity (1 paper, 2023). "Well-designed molecular-based research to dissect the actual mechanism of KRT1 in thyroid autoimmunity is needed." (PMID 38019813, 2023). "Therefore, it also probable that either dysregulated thyroid or blood KRT1 can exhibit breakthrough immune tolerance and subsequently trigger thyroid autoimmunity." (PMID 38019813, 2023).
thyroiditis (1 paper, 2023). Inflammation of the thyroid gland. "It is our future plan to gather mouse serum, skin, thyroid, and peripheral white blood cells at the same time, to quantify KRT1 transcripts of these tissues using the mouse thyroiditis model built by our laboratory, to elucidate the possible origin of elevated serum KRT1 stimulated by the TH." (PMID 38019813, 2023).
tumor (81 papers, 2003 to 2025). "Increased tumor formation was associated with increased cellular proliferation as assessed by Ki67 positivity and decreased squamous differentiation as assessed by keratin 1 and 10 markers expression." (PMID 34185380, 2021). "Finally, we used the Trp(redBODIPY)-labelled cyclopeptide 8 for live-cell and ex vivo imaging of KRT1+ cancer cells and to study their interactions with tumour-associated macrophages in aggressive carcinomas." (PMID 34123261, 2019). "KRT1 knockdown enhanced tumor cell apoptosis and exhibited synergistic effects with conventional radiation and chemotherapy treatments." (PMID 41002590, 2025). "These tumours also showed high levels of KRT1 and IVL expression, indicating squamous differentiation." (PMID 34916592, 2022). "Of the top 20 downregulated DEGs, 10 genes with varied functions such as keratinocyte differentiation (KRT1) and dysregulated tumor–microenvironment interactions were shared between all tumor cohorts and SES." (PMID 35480116, 2022). "Tumor expression profile included an upregulation of basal cell markers such as Krt5, Krt6, Krt14 and Krt1 as well as Cdh3 and Cd44." (PMID 31779626, 2019). "KRT1 protein has been reported to play a tumor suppressive role in various cellular processes like proliferation, cell death, cell cycle, and cytoskeleton organization." (PMID 29212176, 2017). "The overexpression of S100A7 significantly promoted tumor growth and decreased the expression of cytokeratin-1, TG-1, and involucrin in A-431 xenografts compared with the control animals." (PMID 26053695, 2015). "Periostin, keratin-1, nm-23 protein, etc., were up-regulated in tumour stroma; HSP 70, keratin-19, Rho GDP dissociation inhibitor (GDI) β, superoxide dismutase, etc., were down-regulated in tumour stroma." (PMID 26184160, 2015). "The percentages of tumor keratin 1 and 5/6 in CRBP-1High was increased and almost double compared with CRBP-1Low tumors." (PMID 26807202, 2015). "Specifically, in tumor formation the interaction mechanism of keratin 1 and Hsp74 need to be clarified further." (PMID 25050384, 2014). "These tumours also displayed high expression levels of epidermal differentiation genes (such as IVL, LOR and KRT1), indicating that these tumours had undergone squamous metaplasia, and an activation of the WNT/β-catenin signalling pathway (expression of WNT10B and LEF1)." (PMID 34916592, 2022). "The expression levels of KRT1/2/5/6/10/14/15/16/17 were correlated with advanced tumor stage." (PMID 33441834, 2021). "According to the function related to inflammation, angiogenesis, apoptosis, fibrosis and tumor growth, which are closely associated with either the development of DR or VEGF signaling, we were interested in following candidate proteins: APOC1, SERPINA5, TIMP2, and KRT1." (PMID 29541006, 2018). "One additional cluster was characterized by expression of epithelial markers (KRT1, SLPI) and was almost exclusively derived from one tumor (SCH4)." (PMID 38216553, 2024). "This presents a convenient test case for SpatialCorr and we indeed identified strong correlation between expected type 1 and type 2 pairs such as KRT1 and KRT10, as well as KRT5 and KRT14, throughout the epidermis and much of the tumor." (PMID 36590683, 2022). "By contrast, SEMA4B, KRT1, KRT9, FBLN1, and PTGDS are involved in the anti-invasive activity of tumor cells." (PMID 32953262, 2020). "Immunohistochemical localization showed that KRT1, KRT6, and KRT16 were highly elevated in the well-differentiated cells in the center of the tumor rests when compared to the less differentiated cells at the periphery." (PMID 30550540, 2018). "KRT1, KRT6, KRT16 and KRT17 showed strong staining in the well-differentiated cells in the center of the tumor nests when compared to the staining in the peripheral tumor cells." (PMID 30550540, 2018).
tumor (continued). "Cytokeratin 1 (KRT1) was down-regulated in neighbouring and up-regulated in tumour tissue, while the other cytokeratins (KRT5-7-10-14) were all up-regulated in both tissue types compared with normal mucosa." (PMID 27465361, 2016). "Among them, keratin 1(K1) can act as a cell surface receptor in cancer, and KEGG enrichment analysis also shows that cytokine receptor action is more significant; while keratin 17 (K17) plays a role in DNA damage response and tumor initiation." (PMID 36300089, 2022). "The results showed that tumor cells from nonmetastatic tumors expressed high levels of MMP1, KRT1, and MMP13 and low levels of MGST1, FAM133A, and FMO3." (PMID 36569924, 2022).
infection (71 papers, 2009 to 2026). The state of being infected such as from the introduction of a foreign agent such as serum, vaccine, antigenic substance or organism. "Another possibility is that the increased expression of the CASP14 gene is involved in the repair of damage caused by the repression of the FLG and KRT1 genes as a host defense response during infection with T. rubrum." (PMID 30029541, 2018). "In the present study KRT1 was under-expressed after chronic wound in a similar fashion than KRT2 was under-expressed in skin mucus after infection." (PMID 29197330, 2017). "KRT1 is involved in negative regulation of the pro-inflammatory response in the epithelia, and Krt1 was significantly up-regulated at Days 4 and 7 at the site of infection in our model (LFC 1.36 and 1.77, respectively)." (PMID 25901897, 2015). "At 72 h after infection, increased RORα4 expression significantly induced the expression of early and intermediate differentiation markers (keratin 1/10 and involucrin), as well as granular layer markers (loricrin and filaggrin) at both mRNA and protein levels." (PMID 23922987, 2013).
cancer (41 papers, 2004 to 2026). A tumor composed of atypical neoplastic, often pleomorphic cells that invade other tissues. "RNA sequencing analysis identified Keratin-1 (KRT1) as a gene potentially associated with cancer recurrence." (PMID 41002590, 2025). "Moreover, DSG1, C6orf15, SOST, SPRR2A, SERPINB7, MYBPH, and KRT1 were considerably expressed in the high-risk group, indicating their potential roles as cancer-promoting genes in the development of BLCA." (PMID 37664033, 2023). "Additionally, we observed significant expression of CLDN6, CES1, SOST, SPRR2A, MYBPH, CGB5, and KRT1 in the high-risk group, suggesting their potential involvement as cancer-promoting genes in BLCA development." (PMID 37780567, 2023). "Few studies have examined KRT1 in cancer; its expression has been reported in premalignant and malignant oral lesions." (PMID 41002590, 2025). "The methylation on many of arginine methylation sites identified in cultured cells was present in cancer cell samples, such as those on KRT1 and TAF15 proteins, further strengthening the functional importance of PRMT-mediated arginine methylation in cancers." (PMID 33782401, 2021). "The most downregulated circRNAs included both well-characterized cancer-associated circRNAs, such as CDR1as, as well as novel circRNAs, which were derived from host genes IFFO2, KRT1 and POF1B34." (PMID 32108138, 2020). "IGF2 and anti-apoptotic gene KRT1 were significantly overexpressed in MTIs- resistant cancer cells, and exhaustion of IGF2 can restore paclitaxel sensitivity." (PMID 33221769, 2020). "Furthermore, emerging CSRs (EGFR, DLL3, and keratin 1) that may support next-generation TDD platforms for cancer treatment are also highlighted." (PMID 41900872, 2026). "KRT1 is discovered as a novel biomarker in aggressive cancers for its overexpression in epithelial cell surface, and KRT1-targeted reagents could offer innovative therapy for cancer treatments and diagnosis." (PMID 39619568, 2024). "Cancer line analysis indicated significant downregulation of five cytoskeleton proteins, keratins (KRT2, KRT9, KRT1, KRT10)." (PMID 37377864, 2023). "There was also a positive correlation between high EDAR and expression of the skin-specific genes LORICRIN (LOR), KERATIN1 (KRT1) and INVOLUCRIN (IVL), suggesting the occurrence of squamous metaplasia within the EDAR-high cancers." (PMID 34916592, 2022). "This index integrates serum levels of cytokeratin-1 (CK-1), epithelial membrane antigen (EMA), albumin, and alpha-fetoprotein (AFP) into a formula designed to maximize discrimination between HCC and non-malignant liver disease." (PMID 40537682, 2025). "KRT1 was found to be elevated in urospheres (which contain cancer initiating cells) compared to the parent non-tumorigenic UROtsa cell line, which was exposed to arsenite in order to acquire transformed cells." (PMID 35361846, 2022). "Lastly, KRT1high BLCA patients had significantly higher expression of EGFR and MKI67, suggesting that proliferation is potentiated in this group; this complements the survival analysis (high KRT1 is unfavorable in BLCA) and IHC data (KRT1 staining is higher in cancer than normal specimens)." (PMID 35361846, 2022). "Moreover, 19 upregulated proteins (including keratin 1 protein and rheumatoid factor RF-IP20, ratio>1.5) and 8 downregulated proteins (including carbonic anhydrase 1, ratio<0.667) were identified from malignant ascites samples." (PMID 30345303, 2018).
bacterial infection (4 papers, 2020 to 2025). "Plasminogen (PLG) and keratin (KRT1) proteins are expressed in epithelial cells and are important in bacterial infection pathways." (PMID 32765254, 2020).
genetic skin diseases (3 papers, 2019 to 2021). "Keratinopathic ichthyoses (KI) are a group of genetic skin diseases due to mutations in keratin genes KRT1, KRT2, and KRT10 encoding keratins 1, 2 and 10 (K1, K2, K10), respectively, expressed in suprabasal epidermis." (PMID 33081034, 2020). "Ichthyosis with confetti (IWC) is a genodermatosis associated with dominant‐negative variants in keratin 10 (KRT10) or keratin 1 (KRT1)." (PMID 31638346, 2019).
genetic disorders (1 paper, 2020). "In general, KRT1 is highly conserved in mammals, however, molecular defects in keratin intermediate filament-related genes can cause keratinocyte and tissue-specific fragility, accounting for a large number of genetic disorders in skin and its appendages." (PMID 32811876, 2020).
immune diseases (1 paper, 2017). "More work need to be done to elucidate the genetic diversity of KRT1 and the association with immune diseases." (PMID 29028840, 2017).
KRT1 also shares sentences with these, for which no sentence is quoted: meningitis (19 papers); malaria (15); thyroid cancer (8); Kaposi's sarcoma (7); Liver abscess (7); AIDS (6); lymphoma (6); Sepsis (6); atopic dermatitis (5); bacteremia (5); diabetes (3); E. coli infection (3); epidermolysis bullosa simplex (3); leukemia (3); pyelonephritis (3); B-cell lymphoma (2); colitis (2); depression (2); diabetic foot ulcer (2); dry eye syndrome (2); epidermolytic nevus (2); Erythema (2); Graves disease (2); latent infection (2); lupus (2); nasopharyngeal carcinoma (2); Neonatal sepsis (2); nosocomial infection (2); pachyonychia congenita (2); skin tumor (2).
A further 73 diseases each share a sentence with KRT1 in 2 papers or fewer.